CXCR4 (C-X-C motif chemokine receptor 4)
Diseases named in the same sentence as CXCR4 in open-access papers (continued):
Sharing a sentence is not in itself a finding about the gene and the disease.
tumor (continued). "Explicitly, targeting HIF-1α or its downstream regulatory pathways (e.g., CXCL12/CXCR4 axis) at the tumor and stromal cell levels may be a viable strategy to surmount HME-mediated protection of CLL cells." (PMID 37588219, 2024). "Anti-CXCR4-NaGdF4 NDs reveal partial tumor growth inhibition." (PMID 38982161, 2024). "This compartmentalized expression pattern of CXCL12 and CXCR4 indicates that the KS PDX system will be useful to further delineate the communication networks that promote proliferative expansion of KS infected endothelial cells in the tumor microenvironment." (PMID 39386738, 2024). "Our data underscored the T22 carrier’s ability to selectively deliver to CXCR4+ tumor cells." (PMID 39559553, 2024). "Our research indicates that PLOD2 + SAA1 + tumor cells might be capable of communicating with tumor-associated macrophages (TAMs) through specific ligand-receptor pairs, such as MIF-(CD74 + CXCR4), MDK-LRP1 and C3-C3AR1." (PMID 38951896, 2024). "Considering that CXCR4 functions involve the promotion of cell growth, proinflammatory cell recruitment, angiogenesis, and cell migration, it is not surprising that the pathological activation of this receptor favors the development of tumoral disease." (PMID 38791878, 2024). "Furthermore, blockade of CXCL12/CXCR4 pathway prolonged the survival of tumor-bearing mice and reduced tumor burden in several preclinical studies." (PMID 39003350, 2024). "The expression of CXCR4 in tumor‐conditioned neutrophils was synchronized with that of medium‐conditioned neutrophils and remained unaffected by extrinsic factors, which aligns with previous findings indicating that neutrophil aging is an intrinsic circadian process." (PMID 39447112, 2024). "Furthermore, we assessed previous lines of therapy and concurrent diseases to examine their influence on tumor uptake and BM CXCR4-expression." (PMID 38082196, 2024). "Combination therapy enhanced the tumor inflammatory score and supported the idea that anti-CXCR4 treatment may reduce immunosuppression in tumors." (PMID 38612911, 2024). "Also, peptide CXCR4 antagonists have similarly blocked CXCR4 in diverse cancer types, showing potential in enhancing immune function and reducing tumor proliferation." (PMID 39034318, 2024). "Furthermore, the expressions of CD74 and CXCR4 were higher in GrB+ B cells from the tumor group compared to the control group." (PMID 38386050, 2024). "Moreover, the high tracer uptake in certain patients is figured out to be due to the high expression of CXCR4 in tumor cells." (PMID 39431004, 2024). "Furthermore, IL-6, CXCR4, CXCL8, and MMP-9 indicate higher diagnostic utility based on the AUC than the well-established tumor markers, such as CEA and SCC-Ag in OC patients." (PMID 38673838, 2024). "Interestingly, we observed CXCR4 expression gradually increased with tumor invasion through the basement membrane." (PMID 39236316, 2024). "In vitro G2/M growth arrest due to pan-inhibition of Notch has been demonstrated to be rescued by exposure to SDF1, thereby providing evidence that Notch-driven tumor proliferation may be partially mediated by CXCR4/SDF1 signaling." (PMID 39619207, 2024). "Altogether, this finding could potentially indicate that CXCR4 RLT or “cold” chemokine receptor-mediated therapeutic approaches would most likely exert anti-tumor effects in all sites of disease throughout the body." (PMID 38082196, 2024). "As specific tumor marker, CXCR4 was significantly down‐regulated in Group C&E, which may be attributed to the CXCR4 inhibitor AMD3100." (PMID 38774946, 2024).
tumor (continued). "CXCR4 selectively binds the CXC chemokine stromal cell-derived factor-1 (SDF-1), also known as CXCL12, and plays a crucial role in several biological processes, including in cancer biology, where it was associated with tumour dissemination and metastasis." (PMID 38534365, 2024). "For example, MRC1(+)TIE2(Hi)CXCR4(Hi) macrophages present in human breast carcinomas and bone metastases accumulate around blood vessels in tumors after chemotherapy, where they promote tumor revascularization and relapse." (PMID 39516356, 2024). "For example, C-X-C motif chemokine receptor 4 (CXCR4) is commonly overexpressed in tumor-associated MDSCs, and anti-CXCR4 therapy can synergize with anti-PD-1 therapy to increase the survival of GBM tumor-bearing mice." (PMID 39406966, 2024). "In addition to tumor metastasis, CXCR4 is also involved in the modulation of carcinogenic stem cells." (PMID 38791414, 2024). "CXCR4 is a typical seven transmembrane G protein-coupled receptor highly expressed by various human cancers and crucially involved in tumor growth, invasion, angiogenesis, and metastasis, rendering this receptor as an attractive target for cancer diagnosis, treatment, and prognosis 1-4." (PMID 39431004, 2024). "Meanwhile, CXCR4 antagonism via the “patching” removes physical barriers by alleviating desmoplasia and reduces immunological barriers by reversing immunosuppression, which paves the way for T cell penetration and tumor-reactive activity." (PMID 38553476, 2024). "The seven-transmembrane G-protein-coupled chemokine receptor CXCR4 plays an essential role in the homing and retention of tumor cells in the protective bone marrow niches, thereby preventing their culmination by therapeutic agents and increasing the risk of disease relapses." (PMID 39125877, 2024). "Therefore, the identification of CXCR4 inhibitors has a great potential to abrogate tumor metastasis." (PMID 39465008, 2024). "Recent scRNA analysis revealed that CXCR4 was expressed in tumor infiltrates including myeloid cells as well as T-cells and B-cells in the TME, suggesting that CD14 TAMC uniquely may be accompanied by lymphocytes marked by CXCR4." (PMID 38557819, 2024). "Additionally, microRNA-sequencing from SCLC patient serum revealed that miR-1 expression reduces tumor growth and metastasis by targeting the CXCR4/FOXM1/RRM2 axis." (PMID 39114657, 2024). "CXCR4 can be utilized for tumor detection and assessment of therapeutic response by immuno-PET." (PMID 38464386, 2024). "The activation of CXCR4, a stromal cell-derived factor-1 receptor, triggers signalling pathways promoting increased survival, enhanced proliferation, the degradation of the extracellular matrix, drug resistance, and angiogenesis in malignant tumour cells." (PMID 38539419, 2024). "As such, an interim scan targeting CXCR4 on the tumor cell surface may serve as a prognostic biomarker after having initiated locoregional or systemic therapies." (PMID 38896128, 2024). "Moreover, the expression levels of C-X-C motif chemokine receptor 4 (CXCR4) were significantly elevated in tumor stromal cells and tumor colonocytes compared to paired adjacent normal mucosa." (PMID 38464391, 2024). "The median proportion of T cells expressing CXCR4 was lower in the Neo-CT–treated group, which potentially might confer a better migratory capacity of T cells within the tumor microenvironment." (PMID 38335302, 2024). "A phase 1b trial suggested that the oral CXCR4 inhibitor Mavorixafor, in combination with Nivolumab, exhibited potential anti-tumor activity in metastatic ccRCC patients unresponsive to Nivolumab monotherapy, particularly evident in patients with stable disease." (PMID 39014460, 2024). "Until that time, the CXCL12/CXCR4/MDM2/MDMX axis in tumor metastasis is speculative since only the role of in vitro cell migration has been assessed in the current manuscript." (PMID 39766093, 2024).
tumor (continued). "Investigating the largest cohort of patients with solid cancers imaged with [68 Ga]Ga-pentixafor PET/CT to date, CXCR4-positive tumor burden was identified in more than two-thirds of the patients, along with high image contrast indicative for good read-out capabilities." (PMID 38082196, 2024). "Administering CXCL12 in vivo inhibited mouse HCC progression, and this anti‐tumor effect could be abrogated by a CXCR4 inhibitor." (PMID 39422063, 2024). "The novel lutecium‐based rare earth nanoparticles RENPs offer the potential for imaging‐guided tumor delineation with CXCR4 target, radio‐sensitization with ROS production and tumor microenvironment immune activation with immunogenic cell death and immune cell recruitment." (PMID 38774946, 2024). "In addition to chemotaxis, CXCL12 and CXCR4 can induce monocyte differentiation into TAMs, which significantly increases tumor invasiveness." (PMID 39606239, 2024). "Moreover, the specificity and capability of [18F]AlF-NOTA-QHY-04 for in vivo imaging of CXCR4 expression in tumor models and cancer patients were validated." (PMID 39431004, 2024). "In addition, studies have shown that in pancreatic cancer, the SDF-1/CXCR4/SATB-1 axis induces tumor progression and GEM resistance by building a positive feedback loop." (PMID 39075612, 2024). "However, in the GBM model with a permeable BBB, the tumor uptake had an increased SUV of 1.2, mainly due to high CXCR4 expression in the tumor, more than the permeable BBB caused by the tumor." (PMID 39162901, 2024). "CXCR4 is such a receptor as it is predominantly localized in the plasma membrane of tumor cells." (PMID 39457017, 2024). "Furthermore, upregulation of CXCL12γ induces the development of tumor stem and neuroendocrine phenotypes in PCa cells by activating PKCα/NF-κB signaling through CXCR4." (PMID 39092186, 2024). "In many retrospective studies, it was found that CXCR4 is the most widely expressed chemokine receptor in tumor cells, which is responsible for the metastasis of tumor cells to lung, liver and bone marrow, which are the most common metastasis destinations in many cancers." (PMID 39654896, 2024). "This discrepancy may suggest a more complex interaction within the tumor microenvironment, where CXCR4’s impact on survival could be modulated by other factors, including miRNAs and interactions with other signaling pathways." (PMID 39682150, 2024). "Similarly, P. gingivalis Mfa1 and FimA fimbriae also exhibit antiapoptotic activity by upregulating C-X-C chemokine receptor type 4 (CXCR4) and downregulating Forkhead Box O1/3 (FOXO1/3), which are associated with tumor progression." (PMID 38807771, 2024). "The CXCL12/CXCR4 axis plays a role in the migration of ASCs towards the tumor site." (PMID 39519109, 2024). "Interestingly, nuclear DR5 regulates CXCR4 expression through inhibiting let-7 maturation, leading, as a consequence, to the expression of HMGA2 and CXCR4, and bone metastases formation of breast primary tumours." (PMID 38534365, 2024). "CXCR4 is a chemokine receptor involved in tumor progression, angiogenesis, and metastasis." (PMID 38893721, 2024). "Notably, QRHX inhibits inflammation and the CXCL12/CXCR4/JAK2/STAT3 signaling pathway, thereby modulating tumor-associated macrophages in murine models and suppressing tumor growth." (PMID 38920657, 2024). "Indeed, CXCR-4 targeting significantly reduced total tumor burden and metastases in different preclinical models." (PMID 39003350, 2024). "In addition, we performed a [68GA]Pentixafor PET/CT scan with CXCR4-directed radioligand in one patient to evaluate the CXCR4 expression in the tumor aiming at a potential CXCR4-radioligand therapy." (PMID 39411551, 2024). "Additional Phase II trials will assess whether a CXCR4 blockade with BL-8040 improves the anti-tumor efficacy of anti-PD1 treatment." (PMID 38339310, 2024).
tumor (continued). "The CXCL12/CXCR4 axis can modulate the immune microenvironment of tumors by attracting regulatory T cells (Tregs) and myeloid-derived suppressor cells (MDSCs), which suppress anti-tumor immune responses." (PMID 39682247, 2024). "However, the role of immune cells in the tumor microenvironment is a very interesting field, and to fully elucidate the effects of CXCR4 inhibitors on tumors, the effects of CXCR4 inhibitors on the tumor immune system should be examined." (PMID 39001388, 2024). "Furthermore, targeting CXCR4 with AMD3100 suppressed tumor growth in vitro and in vivo and synergized with docetaxel in trastuzumab-resistant cell lines and in a trastuzumab-resistant xenograft mouse model." (PMID 39001456, 2024). "Furthermore, the interaction between MM cells and cancer-associated fibroblasts (CAFs) via adhesion molecules such as CXCL12/CXCR4 and integrins is essential for promoting CAFs’ tumor-supporting functions." (PMID 38560563, 2024). "CXCR4 inhibition results in impaired tumor revascularization and regrowth after chemotherapy." (PMID 39516356, 2024). "Furthermore, anti-CXCR4-NaGdF4 NDs and Try-NaGdF4 NDs treated tumor-bearing mice were sacrificed at 2 and 24 h post-injection, respectively, and the amounts of Gd in tumors were determined by the ICP-MS measurements." (PMID 38982161, 2024). "In addition to targeting CXCR4, the anti-tumor effects of NOX-A12 (olaptesed pegol), an L-RNA aptamer inhibitor of CXCL12, have been evaluated in combination with anti-PD1." (PMID 38339310, 2024). "Next, target specificity was further evaluated in A549/CXCR4 and A549 tumor-bearing mice." (PMID 39431004, 2024). "Taken together, these data suggest that tumor-derived EVs may increase the transcriptional level of CXCR4 in neutrophils, skewing their phenotype to a pro-tumor polarization, allowing tumor cell survival." (PMID 39698539, 2024). "Treatment with a CXCR4 antagonist promoted CD8+ T cell recruitment to the tumor." (PMID 37895882, 2023). "Blockade of the CXCR4 signaling is hypothesized to not only decrease tumor angiogenesis but also decrease the number of cancer stem cells and increase mobilization and recruitment of effector T cells into the TME." (PMID 37114134, 2023). "Furthermore, it has been confirmed that lymph node metastasis can be a source of tumor cells for distant metastases in solid tumors which was related to CXCR4/CXCL12 axis." (PMID 36762192, 2023). "Just to cite a few examples, it has been reported that CXCL12, highly expressed in tumor-associated LVs but not in normal ones, promotes the dissemination of CXCR4-expressing cancer cells toward distant organs that highly express CXCL12." (PMID 38068914, 2023). "Furthermore, overexpression of CXCR4 in tumor tissues was shown to have a high correlation with tumor aggressiveness and elevated risks of metastasis and recurrence." (PMID 37375261, 2023). "Notably, tumor cells express high levels of CXCR4 and produce CXCL12, which acts in an autocrine and paracrine manner." (PMID 38188016, 2023). "Additional subclonal hits such as CXCR4 and MAP2K1 mutations could be acquired during tumor progression." (PMID 36797797, 2023). "Similarly, tumor VEGF-C-mediated stimulation of LEC C-X-C motif chemokine receptor 4 (CXCR4) expression increases chemotactic responsiveness to peritumoral CXCL12 gradients." (PMID 38201272, 2023). "Using IF for CD31 (endothelial cell marker), desmin (perivascular cell markers), and CA-IX (hypoxia marker), we found a site-dependent effect on tumor vasculature and hypoxia in response to CXCR4 inhibition, with statistically significant changes or strong trends only in the metastatic PCa lesions." (PMID 36831366, 2023). "T22-GFP-H6 nanoparticles could effectively target and selectively internalize in several CXCR4+ tumor cells, such as colorectal cancer, diffuse large B cell lymphoma and head and neck squamous cell carcinoma tumor." (PMID 36762192, 2023).
tumor (continued). "We found that NUP107 was positively correlated with chemokines such as CCL28 and CXCL8 (r = 0.310, p < 0.001), and the chemokine receptors CCR8 and CXCR4 suggesting that NUP107 overexpression may recruit immune cells to the tumor tissues." (PMID 36952458, 2023). "increased stromal TGF-β may induce the expression of epithelial CXCR4, which allowed stromal SDF-1 to activate the PI3K/AKT pathway in epithelial cells, leading to tumour development and predisposing cells to further malignant progression." (PMID 37162544, 2023). "The expression of CXCR4/CXCL12 was reported to be increased due to the hypoxic tumor environment." (PMID 37484803, 2023). "TAM expression of CXCR4 is induced by tumor cell-derived transforming growth factor-β (TGF-β) which enables the migration of these TAMs to the endothelium which is orchestrated by Pv fibroblasts, phenotypically distinct from pericytes (desmin−), which express high levels of CXCL12." (PMID 37199172, 2023). "Mechanistically, butein is known to: (i) regulate BCL2/Bax ratio, induce caspase activity, and consequently drive apoptosis; (ii) stimulate DR5 and mediate caspase-3-dependent apoptosis in TRAIL-resistant cells; and (iii) inhibit NFκB and dictate NFκB-mediated CXCR4-dependent tumor cell migration." (PMID 38249515, 2023). "Additionally, elevated CXCR4 levels in normal cells led to an increase in the migration and invasion of tumor cells." (PMID 37176108, 2023). "Thus, CXCR4 is a promising therapeutic target because the intracellular delivery of siRNA (knockdown) or CXCR4 blockade by antagonist can prevent tumor progression in mice." (PMID 38004925, 2023). "Intriguingly, CXCR4 expression in tumor cells exhibited different patterns." (PMID 37280713, 2023). "Therefore, we studied the relationship between CXCR4 and tumor immunity features to determine the prognostic value of CXCR4 in NSCLC." (PMID 36308553, 2023). "Ontology analysis reveals that ccRCC DMCpGs map to genes linked to tumor driver and anticancer therapy pathways including PD-1 immunotherapy, invasion/metastasis (epithelial-mesenchymal transition (EMT) and CXCR4 signaling), and inflammation (interferon and IL8 signaling)." (PMID 37120552, 2023). "Moreover, hypoxia promotes pDC recruitment to tumor tissues through the hypoxia-inducible factor 1α (HIF-1α)/SDF-1/CXCR4 pathway." (PMID 37817484, 2023). "Besides, MIF-(CD74+CXCR4) and MIF-(CD74+CD44) pathways were widespread and are associated with multiple cell types in the tumor and normal tissues." (PMID 37335089, 2023). "Finally, a similar mechanism attracted and trapped circulating murine CXCR4-expressing melanoma tumor cells in vitro and in vivo after subcutaneous injection, thereby reducing lung metastasis." (PMID 36725964, 2023). "Despite their potential use in a wide spectrum of cancers, it is unclear whether CXCR4 or FAP expression clearly mark distinct tumor subgroups or certain tumor microenvironments." (PMID 36672341, 2023). "Given that CXCR4 antagonists increase CD8+ T cell infiltration into tumor tissues and the expression of CXCR4 in these cells, it is plausible that the recruitment of pro-inflammatory immune cells induced by LPA1 is partially due to LPA1’s inhibitory effect on CXCR4 in these cells." (PMID 37749552, 2023). "Notably, the CXCL12/CXCR4 axis holds significant value in cancer studies as it contributes to tumor development as well as the transition of ADMSCs into CAFs." (PMID 38004606, 2023). "Indeed, the presence of CXCR4 overexpression strengthens the ability of several tumor types to migrate and metastasize into organs while also secreting high levels of CXCL12, a known attractant of cancer cells." (PMID 36980182, 2023). "We next examined the changes induced by CXCR4 inhibition on the tumor microenvironment of PCa." (PMID 36831366, 2023).